CAMKK1 (calcium/calmodulin dependent protein kinase kinase 1)
Description:
Calcium/calmodulin-dependent protein kinase that belongs to a proposed calcium-triggered signaling cascade involved in a number of cellular processes. Phosphorylates CAMK1, CAMK1D, CAMK1G and CAMK4. Involved in regulating cell apoptosis. Promotes cell survival by phosphorylating AKT1/PKB that inhibits pro-apoptotic BAD/Bcl2-antagonist of cell death.
Synonyms: CAMKKA; DKFZp761M0423; MGC34095
Tractability: Small molecule: a structure with a bound ligand is known; a high-quality ligand is known; it belongs to a druggable protein family. PROTAC: it is named in the literature on targeted protein degradation; ubiquitination databases record sites on it; its protein half-life has been measured; a small molecule that binds it is known.
Target class: Enzyme; Protein Kinase; Kinase; Other protein kinase group; Other protein kinase CAMKK family; Other protein kinase Meta subfamily
Chemical probes: SGC-CAMKK2-1 (high quality), STO609
Gene: Protein-coding gene on chromosome 17 (3,860,315 to 3,894,891, reverse strand). Ensembl gene ENSG00000004660.
Subcellular location: Cytoplasm; Nucleus
Subcellular location (Human Protein Atlas): Cytosol
Pathways (Reactome):
Neuronal System: Activation of RAC1 downstream of NMDARs; CREB1 phosphorylation through the activation of CaMKII/CaMKK/CaMKIV cascasde
Signal Transduction: CaMK IV-mediated phosphorylation of CREB
Gene Ontology:
Molecular function: protein binding; calcium/calmodulin-dependent protein kinase activity; calmodulin binding; ATP binding; protein kinase activity; protein serine kinase activity
Biological process: intracellular signal transduction
Cellular component: cytoplasm; cytosol; nucleoplasm; nucleus
Genetic constraint (gnomAD): Loss-of-function variants: 20 observed, 61.76 expected, observed/expected ratio (o/e) 0.32, 90% interval 0.23 to 0.47. The upper end of that interval is the gene's LOEUF score, 0.47, which puts it in group 2 of 6, group 1 being the genes least tolerant of losing a copy. Missense variants: 588 observed, 670.76 expected, observed/expected ratio (o/e) 0.88, 90% interval 0.82 to 0.94. Synonymous variants: 253 observed, 274.92 expected, observed/expected ratio (o/e) 0.92, 90% interval 0.83 to 1.02.
Homologues: Orthologues: chimpanzee CAMKK1 (99% identical), macaque CAMKK1 (99% identical), pig CAMKK1 (95% identical), guinea pig CAMKK1 (94% identical), mouse Camkk1 (93% identical), rat Camkk1 (93% identical), dog CAMKK1 (93% identical), rabbit CAMKK1 (86% identical), tropical clawed frog camkk1 (71% identical), zebrafish camkk1a (64% identical), zebrafish camkk1b (60% identical), Caenorhabditis elegans ckk-1 (46% identical), and 1 more. Paralogues in human: CAMKK2 (60% identical), CAMK2A (24% identical), CAMK2D (24% identical), CAMK2G (24% identical), CAMK2B (24% identical), DCLK1 (24% identical), DCLK2 (23% identical), STK11 (22% identical), CAMK1D (20% identical), CAMK1G (20% identical), DCLK3 (20% identical), CAMK1 (19% identical), and 10 more.
Diseases named in the same sentence as CAMKK1 in open-access papers:
CAMKK1 is named in the same sentence as 19 diseases in open-access papers, as found by Europe PMC text mining. Sharing a sentence is not in itself a finding about the gene and the disease. The quoted sentences say what the papers report.
lung carcinoma (4 papers, 2021 to 2022). "As for CAMKK1, it is reported that the polymorphism of CAMKK1 rs7214723 was correlated with an increase in lung cancer risk." (PMID 35410586, 2022). "In this study, we evaluated the association between the SNP rs7214723 in CAMKK1 and prognosis using blood samples from 839 Chinese patients with lung cancer." (PMID 34868969, 2021). "Rudd conducted a large-scale genome-wide association study among British patients, analyzing 1529 cases and 2707 controls, and found that the rs7214723 (E375G) polymorphism in CAMKK1 was a susceptibility locus of lung cancer in the UK population." (PMID 34868969, 2021). "The association between CAMKK1 SNP rs7214723 as well as the prognosis and survival of patients with lung cancer was evaluated." (PMID 34868969, 2021). "Association between CAMKK1 SNP rs7214723 in genotype models and prognosis in Chinese patients with lung cancer." (PMID 34868969, 2021). "The findings of Rudd’s and Chen’s studies on 1529 British and 320 Chinese patients, respectively, with lung cancer showed that the SNP, rs7214723, in the CAMKK1 gene can increase the risk of lung cancer." (PMID 34868969, 2021). "In conclusion, our results provided the first evidence that CAMKK1 rs7214723 T > C is associated with poor prognosis among patients with lung cancer, playing a more significant role depending on sex, age, smoking status, histology and TNM stage." (PMID 34868969, 2021). "First, this result should be validated with independent studies or meta-analysis, and more extensive prospective studies are needed in the future to further evaluate the association between the CAMKK1 SNP rs7214723 and lung cancer prognosis." (PMID 34868969, 2021). "Previous studies have mainly focused on analyzing the association between the CAMKK1 gene SNP rs7214723 and the risk of lung cancer." (PMID 34868969, 2021). "Association between CAMKK1 polymorphisms in gene model and prognosis in Chinese patients with lung cancer." (PMID 34868969, 2021). "Annexin V-FITC staining assay was performed to determine whether CAMKK1 rs7214723 is associated with lung cancer progression, mediated by affecting the apoptosis process." (PMID 34868969, 2021). "Association between CAMKK1 polymorphisms and prognosis in Chinese patients with lung cancer." (PMID 34868969, 2021). "CAMKK1 SNP rs7214723 may be a significant prognostic factor for the risk of death among patients with lung cancer." (PMID 34868969, 2021). "Our results indicate that rs7214723 T > C is associated with a better prognosis among patients with lung cancer, which may be due to the amino acid change in the kinase domain of CaMKK1." (PMID 34868969, 2021). "To further investigate whether CAMKK1 SNP rs7214723 is associated with lung cancer progression, we collected peripheral blood samples from 839 patients with a confirmed lung cancer diagnosis before treatment initiation and performed genotyping and patient follow-up." (PMID 34868969, 2021). "E375G reduces the activation ability of CaMKK1 on the downstream kinase and weakens the effect of its downstream pathway in terms of promoting the growth of lung cancer cells and inhibiting their apoptosis, which ultimately leads to a better prognosis." (PMID 34868969, 2021). "The candidate-gene associations explored in this study focused on the important locus of the CAMKK1 gene rs7214723 to further investigate the effect on lung cancer prognosis of the SNP at this locus." (PMID 34868969, 2021). "The activation of AMPK, which is also induced by CaMKK1, can inhibit the growth and promote the apoptosis of lung cancer cells." (PMID 34868969, 2021). "We investigated the association between a common non-synonymous single nucleotide polymorphism (SNP), rs7214723, in the Ca2+/calmodulin-dependent protein kinase kinase 1 (CAMKK1) gene and the prognosis of patients with lung cancer." (PMID 34868969, 2021).
lung carcinoma (continued). "We also hypothesized that the smoking factor increases the effect of SNP rs7214723 on the function of CAMKK1 to a certain extent, thereby delaying the progression of the lung cancer tumor, and subsequently leading to a better prognosis." (PMID 34868969, 2021). "However, no studies have reported on the association between the CAMKK1 SNP rs7214723 and the prognosis of lung cancer." (PMID 34868969, 2021). "Therefore, we hypothesize that CAMKK1 may also play an essential role in the development of lung cancer." (PMID 34868969, 2021). "BAG6 rs1077393 was the most important predictor among all SNPs in the lung cancer prediction XGBoost model, followed by TERT rs2735845 and CAMKK1 rs7214723." (PMID 35499292, 2022).
diabetes (2 papers, 2021 to 2025). "CAMKK1 has been implicated in appetite and satiety regulation; however, its role in obesity or type 2 diabetes mellitus (T2DM) remains unexplored." (PMID 40965347, 2025). "However, future longitudinal and mechanistic studies are needed to confirm the hypothesis that CAMKK1 elevations are significantly and causally associated with complications due to diabetes in patients with T2DM." (PMID 40965347, 2025). "However, higher CAMKK1 was significantly associated with having complications due to diabetes (standardised β = 1.060, p = 0.010), and this effect was stronger in older individuals (standardised β = 0.041, p = 0.005) as well as in individuals with higher BMI (standardised β = 0.015, p = 0.029)." (PMID 40965347, 2025). "In this cross‐sectional study, the primary aim was to confirm whether CAMKK1 is elevated in individuals with diabetes." (PMID 40965347, 2025).
acute myocardial infarction (1 paper, 2022). Necrosis of the myocardium, as a result of interruption of the blood supply to the area. "Moreover, the direct overexpression of CaMKK1 in infarcted tissue using a CaMKK1-encoding plasmid also significantly improved ejection fraction and decreased infarct size after acute myocardial infarction." (PMID 36555778, 2022). "In rats, injections in the heart of conditioned media from MSCs overexpressing CaMKK1 showed improvement in cardiac function after acute myocardial infarction, with increased vascular density and decreased scar tissue." (PMID 36555778, 2022).
glioma (1 paper, 2013). A benign or malignant brain and spinal cord tumor that arises from glial cells (astrocytes, oligodendrocytes, ependymal cells). "Curiously, CAMKK1 may be related to glycolytic activation induced by human cytomegalovirus (HCMV), and while controversial, HCMV expression is reported in gliomas." (PMID 24039668, 2013).
melanoma (1 paper, 2022). A malignant, usually aggressive tumor composed of atypical, neoplastic melanocytes. "Another genomic subtype, triple WT melanoma, had DE mostly affecting Ca2+/calmodulin-dependent protein kinase (in addition to RTKs), and we found CAMKK1 expression had a negative correlation with survival." (PMID 35560144, 2022).
Obesity (1 paper, 2025). Accumulation of substantial excess body fat. "In particular, the direct association between CAMKK1 and leptin was observed as attenuated in individuals with obesity, while the direct association between CAMKK1 and blood glucose or TNFα was strengthened in patients with T2DM." (PMID 40965347, 2025). "Present results offer persuading evidence for elevated CAMKK1 levels in both individuals with obesity and patients with T2DM in comparison to controls." (PMID 40965347, 2025). "In turn, individuals with obesity exhibited lower CAMKK1, lower glycemia, lower TNFα and higher ghrelin and leptin in comparison to patients with T2DM." (PMID 40965347, 2025). "The present work shows how CAMKK1 expression is elevated in both individuals with obesity and patients with T2DM, in comparison to controls." (PMID 40965347, 2025). "CAMKK1 serum levels in individuals with obesity (n = 3,061), patients with T2DM (n = 4,910) and controls (n = 44,257) were retrieved and compared (age, body mass index—BMI and sex‐adjusted ANCOVA)." (PMID 40965347, 2025). "An association between CAMKK1 and leptin was observed in both controls and individuals with obesity, but not in patients with T2DM." (PMID 40965347, 2025). "The attenuation of the relationship between CAMKK1 and leptin in individuals with obesity may also suggest that other metabolic factors may be involved in leptin‐binding cascades." (PMID 40965347, 2025). "Patients with T2DM had higher CAMKK1 in comparison to both individuals with obesity and controls." (PMID 40965347, 2025). "In this perspective, future research may validate CAMKK1 and other CAMKs as molecular targets for the treatment of either obesity or T2DM." (PMID 40965347, 2025). "The positive association between CAMKK1 and leptin was attenuated in individuals with obesity in comparison to controls, but no similar effect was detected in patients with T2DM." (PMID 40965347, 2025). "CAMKK1 associations with appetite‐regulating, metabolic and inflammatory factors were perturbed by T2DM, with preliminary evidence of diverging patterns of alterations within both obesity and T2DM (i.e., attenuated satiety signalling for obesity; strengthened inflammatory elevation for T2DM)." (PMID 40965347, 2025). "Elevated CAMKK1 levels were observed in patients with T2DM, in comparison to both individuals with obesity and controls." (PMID 40965347, 2025). "CAMKK1 was elevated in patients with T2DM, in comparison to both individuals with obesity and controls (post hoc comparison, Tukey‐adjusted p = 0.010 and p = 0.044, respectively)." (PMID 40965347, 2025). "The present work offers compelling evidence that CAMKK1 serum levels are increased in patients with T2DM, in comparison to both individuals with obesity and controls." (PMID 40965347, 2025). "In fact, differences in CAMKK1 serum levels between individuals with obesity and controls were not significant after accounting for BMI, indicating that CAMKK1 serum levels were not further elevated beyond what explained by BMI alone in this population." (PMID 40965347, 2025). "By contrast, the positive association between CAMKK1 and TNFα was strengthened in patients with T2DM, but not individuals with obesity." (PMID 40965347, 2025). "In contrast to analyses performed within‐groups, the positive association between CAMKK1 and blood glucose here reached statistical significance but was observed only in patients with T2DM (i.e., neither controls, nor individuals with obesity)." (PMID 40965347, 2025). "However, to the best of the authors' knowledge, no previous study has described either CAMKs or CAMKK1 serum levels in either individuals with obesity or patients with T2DM." (PMID 40965347, 2025).
cancer (4 papers, 2015 to 2025). A tumor composed of atypical neoplastic, often pleomorphic cells that invade other tissues. "This may be related to the excessive activation of CAMKK1 and its downstream AMPK signaling pathway caused by CAMKK1 rs7214723 T > C. These findings all prove the important role of CAMKK1 in cancer development." (PMID 34868969, 2021). "Stratified analysis showed that the CAMKK1 rs7214723 CC genotype and recessive CC genotype conferred a significantly decreased risk of death in patients who were male, had a smoking history, or had stage III + IV cancer, compared with the TT and TT + TC genotypes." (PMID 34868969, 2021). "The understudied multi-functional CaMKs (CAMK1D, CAMK1G, CAMKK1, PNCK) are overexpressed in 12 cancers, with PNCK being overexpressed in 9 alone." (PMID 33205077, 2020). "By focusing on a number of genes, selected because of their reported roles in human cancer (53BP1, CCND3, CLDN7, WNT5B, CAMKK1), we demonstrate the potential impact of this on the translational readout in each cellular context." (PMID 26589636, 2015).
infection (1 paper, 2025). The state of being infected such as from the introduction of a foreign agent such as serum, vaccine, antigenic substance or organism. "Naïve Huh7 cells inoculated with cell- culture-produced infectious HEV particles did not affect the expression of AMPKα or its upstream regulatory kinase genes CAMKK1, CAMKK2 and STK11 at the transcriptional level at 24 h post-infection." (PMID 40074929, 2025).
metabolic disease (1 paper, 2025). A congenital disorder (due to inherited enzyme abnormality) or acquired (due to failure of a metabolically important organ) disorder resulting from an abnormal metabolic process. "An important consideration is thus whether the observed increase in serum CAMKK1 represents a causal factor in the pathophysiology of T2DM or a secondary consequence of metabolic disease." (PMID 40965347, 2025).
CAMKK1 also shares sentences with these, for which no sentence is quoted: cardiovascular diseases (2 papers); neoplasia (2); breast carcinoma (1); breast tumours (1); heroin addiction (1); Hypertension (1); lung squamous cell carcinoma (1); neuropathy (1); prostatic cancer (1); type 2 diabetes mellitus (1).